ATF3 (activating transcription factor 3)
Diseases named in the same sentence as ATF3 in open-access papers (continued):
Sharing a sentence is not in itself a finding about the gene and the disease.
breast cancer (continued). "Activating transcription factor 3 (ATF3) is a stress-induced transcription factor (e.g., by DNA damage, oxidative stress, and cellular injury) that plays an important role in the progression of breast cancer and other tumor diseases." (PMID 38244591, 2024). "Paclitaxel has also been shown to increase CTCs in breast cancer and facilitate metastatic cell seeding in the lung by upregulating the stress-inducible gene ATF3 in nonmalignant host cells." (PMID 38654356, 2024). "ATF3 has been reported to play dichotomous roles by enhancing normal mammary epithelial cell apoptosis and by promoting breast cancer cell proliferation and a similar situation was observed in TSCCs." (PMID 33539340, 2021). "Both its derivatives exerted pro-apoptotic action on the breast cancer MCF-7 line, where treatment with 10 nM of 4HPTTNPB resulted in a 10–20-fold increase in the induction of pro-apoptotic markers ATF3, GADD34, BBC3, and NOXA, marking its great potential as an anti-cancer treatment." (PMID 33809565, 2021). "Even in the noncancer host cells, expression of ATF3 dispenses a pro-metastatic microenvironment in the lung for chemotherapy-induced metastasis of the primary breast cancer cells." (PMID 35052581, 2021). "Using the pre-treatment lung colonization model, we found that chemotherapy enhances the ability of breast cancer cells to colonize the lung in the WT mice but not the Atf3 KO mice." (PMID 34298975, 2021). "Unsupervised hierarchical clustering of the human and mouse expression data illustrated that human samples from the basal-like subtype group clustered with the ATF3 tumors, whereas other human breast cancer subtypes did not." (PMID 33652981, 2021). "Furthermore, ATF-3 inhibits miR-590-3p expression to modulate the miR-590/GOLPH3 pathway and, thus, regulate the proliferation of breast cancer cells." (PMID 32922364, 2020). "Furthermore, ATF-3 inhibits miR-590-3p expression to regulate the miR-590/GOLPH3 pathway and, thus, modulates breast cancer cell proliferation." (PMID 32922364, 2020). "(c) Although functionally important in the breast cancer cells (a and b), Atf3 expression in the cancer cells does not correlate with worse outcome in breast cancer patients." (PMID 30373101, 2018). "This study not only uncovered the ATF-3/miR-590/GOLPH3 signaling pathway on regulating the breast cancer proliferation, but provides a new diagnosis marker and therapeutic target based on miRNA regulation for future breast cancer clinical treatment." (PMID 29534690, 2018). "(d) Studies using breast cancer models comparing WT and KO mice indicated that Atf3 in the non-cancer cells promotes metastasis." (PMID 30373101, 2018). "Previous study has showed that there is a negative feedback regulation of miR-590 and ATF-3 in breast cancer." (PMID 29534690, 2018). "Microarray analysis comparing the populations in which the reporter construct is active versus inactive showed that positive cells expressed higher mRNA levels of cytokines (IL-8, IL-6, TNF) and genes (such as ATF3, SNAI2, and KLF6) previously related with the CSC phenotype in breast cancer." (PMID 25414831, 2014). "The positive expression rate of ATF3 was 76.3% (87/114) in breast cancer tissues, whereas the rate was 13.2% (15/114) in adjacent normal breast tissues." (PMID 24494067, 2013). "We analyzed the expression of 9 Wnt genes by qPCR in mammary tumors derived from parous BK5.ATF3 mice, and in normal, young adult mammary glands of non-transgenic and transgenic mice." (PMID 21304988, 2011). "Non-parous, BK5.ATF3 females do not develop mammary tumors, and their mammary glands do not express high levels of β-catenin mRNA, do not exhibit nuclear localization of β-catenin, and are unable to activate the TOPGAL reporter gene." (PMID 21304988, 2011).
breast cancer (continued). "Strong nuclear expression of ATF3 in the mammary tumor cells was detected in 18% of the tumors overall; none of the normal samples in these arrays showed nuclear ATF3 expression." (PMID 18808719, 2008). "Transgenic mice with overexpression of activating transcription factor 3 (ATF3) have been shown to develop cardiac remodeling, including LV hypertrophy and systolic dysfunction, and showed enhanced tumor growth in orthotopic breast cancer and xenograft lung cancer models." (PMID 38279150, 2024). "ATF3 promotes colon cancer metastasis and is described to build a stable complex with Smad4 that could be responsible for the activation of genes that participate in TGF-β1-mediated breast cancer progression." (PMID 38658567, 2024). "Finally, the authors suggested that modulating ATF3 expression or its downstream targets, such as MET, might be a potential therapeutic method for breast cancer therapy, especially in patients with severe metastatic illness." (PMID 38046946, 2023). "Moreover, recent reports showed that ATF3 expressed in stromal cells and noncancer host cells promoted breast cancer cell dissemination into the lung and chemotherapy-exacerbated breast cancer metastasis, respectively." (PMID 34728784, 2021). "In host cells within the tumor microenvironment, it was recently demonstrated that mice lacking ATF3 (ATF3-KO) or JDP2 (JDP2-KO) display a reduced rate of metastasis in polyoma middle T-antigen (PyMT) breast carcinoma mouse model and/or Lewis Lung Carcinoma (LLC)." (PMID 30670778, 2019). "This study not only suggests that the ATF-3/miR-590/GOLPH3 signaling pathway is critically involved in the proliferation of breast cancer cells, but provides a novel therapeutic target and new insight base on epigenetic regulation for future breast cancer diagnosis and clinical treatment." (PMID 29534690, 2018). "In this study, we collected 114 cases of breast cancer and 114 cases of adjacent non-tumor breast tissues, and explored the expression of ATF3 protein to determine whether or not ATF3 expression influences breast cancer malignancy and clinical outcome." (PMID 24494067, 2013). "A significant difference in overall survival rate was also found between the patients with positive expression of ATF3 protein and those with negative expression (P=0.041), suggesting that ATF3 may be a new prognostic indicator for breast cancer patients." (PMID 24494067, 2013). "However, until recently, there have been no studies investigating the clinical significance of ATF3 in human breast cancer." (PMID 24494067, 2013). "ATF3 expression was undetectable in the negative control samples and ATF3 protein was weakly expressed mostly in the adjacent normal breast tissues, however, in breast cancer cells, there was a remarkable increase." (PMID 24494067, 2013). "In breast cancer, CXCL8 expression level strongly correlated with activating transcription factor 3 (ATF3), c-Jun and JunB, members of the AP-1 transcription factor complex, and ATF3 and JunB were also observed to be upregulated in the metastatic osteosarcoma samples investigated here." (PMID 22518090, 2012). "Many of the changes in gene expression seen in ATF3-induced mammary tumors may not be due to direct effects of ATF3 on the transcription of the affected gene, but to indirect effects related to changes in signaling pathways." (PMID 21304988, 2011). "On the other hand, although various evidence have all come to indicate that activating transcription factor 3 (ATF3) may be high expressed in various cancer cells, there have been no studies investigating the clinical significance of ATF3 in human breast cancer until recently." (PMID 30117642, 2018). "Importantly, FOXA1, ATF2, ATF3 and many other known key regulators in breast cancer could not be incorporated by any NCA algorithm because of the necessary conditions." (PMID 26537518, 2015).
breast cancer (continued). "In MMTV.neu mammary tumors in which the Wnt/β-catenin pathway is not involved, expression of Axin2 was extremely low (relative expression 0.01 compared to BK5.ATF3 mammary glands, p<0.01, data not shown), and Dkk4 was undetectable." (PMID 21304988, 2011). "Previous studies on human breast cancer, lung cancer, skin cancer, and CRC have demonstrated increased ATF3 expression in cancer tissues/cells compared with that in normal tissues/cells." (PMID 30246803, 2018).
colorectal cancer (57 papers, 2007 to 2026). A primary or metastatic malignant neoplasm that affects the colon or rectum. "KLF4 and EGR1 together have been implicated in inducing ATF3 transcription and subsequent apoptosis in resveratrol-treated human colorectal cancer cells." (PMID 35746681, 2022). "Since the Wnt signaling pathway is one of those that are frequently mutated in human colorectal cancer, ATF3 is a candidate biomarker and target for cancer treatment and prevention." (PMID 29966001, 2018). "In HCT116 human colorectal cancer cells, the expression of ATF3 mRNA and protein were correlated to β-catenin gene mutations." (PMID 29966001, 2018). "Activating transcription factor 3 (ATF3) has been reported to be associated with apoptosis in colorectal cancer." (PMID 27043582, 2016). "In this study, we for the first time provide evidence that A. distichum exerts anti-cancer effect, which especially is associated with ATF3 activation in human colorectal cancer cells." (PMID 25494848, 2014). "There is growing evidence that activating transcription factor 3 (ATF3) is linked to cell growth arrest and apoptosis in colorectal cancer." (PMID 24962785, 2014). "The effect of phlorofucofuroeckol A has been investigated in human colorectal cancer (HT-29) cells for its anticancer property and results shown a high expression of activating transcription factor 3 (ATF3) which is associated with apoptosis in colorectal cancer." (PMID 35736190, 2022). "The current data demonstrate that PFF-A increases ATF3 expression through transcriptional regulation, which might be associated with the induction of apoptosis in human colorectal cancer cells." (PMID 27043582, 2016). "Here, for the first time, we report that ginger leaves leads to transcriptional activation of activating transcription factor 3 (ATF3) which may be associated with the reduction of cell viability and induction of apoptosis in human colorectal cancer cells." (PMID 25338635, 2014). "In human colorectal cancer cells, ATF3 overexpression increased expression of the pro-apoptotic marker cleaved PARP (Poly(ADP-ribose) Polymerase) and ATF3 directly binds to the promoter and represses transcription of the pro-survival gene Bcl-xL." (PMID 41198649, 2025). "In conclusion, targeting the ATF3/CBS signaling axis along with an amino acid-restricted dietary regimen holds significant clinical potential for treating colorectal cancer." (PMID 38490069, 2024). "Research has found that Patulin induces transcription factor EGR-1 phosphorylation through increased oxidative stress, thereby enhancing ATF3 expression and promoting apoptosis in colorectal cancer cells." (PMID 38255898, 2024). "A study proposed that phlorofucofuroeckol A (PFF-A) has anti-cancer properties by inducing ATF3 expression via the p38 MAPK/JNK-mediated pathway in human colorectal cancer cells." (PMID 37816731, 2023). "For example, Zhu and his colleagues found the ATF3 protein in colorectal cancer patients was statistically up-regulated, but the ATF3 mRNA level was without significant change, suggesting a discrepancy between ATF3 protein and mRNA levels." (PMID 36145135, 2022). "The role of ATF3 in colorectal cancer is yet to be determined, but the tumor suppressor MXD1 was deciphered to be targeted by MiR-19a/b in gastric cancer." (PMID 34831349, 2021). "ATF3 enhances sensitization of human colorectal cancer cells to TNF-related apoptosis-inducing ligand (TRAIL)-mediated apoptosis through endoplasmic reticulum (ER) stress." (PMID 32922364, 2020). "Other reports showed ATF3 as inhibitor of invasion and migration both in colorectal cancer and ovarian cancer cells." (PMID 33050633, 2020).
colorectal cancer (continued). "ATF3, an adaptive-response gene, exhibits tumor suppressor function in the development of human colorectal cancer." (PMID 30060617, 2018). "In human colorectal cancer, ATF3 expression is reportedly lower than that in the surrounding non-cancerous tissue, and the RNAi-mediated silencing of ATF3 increased cancer cell migration both in vitro and in vivo." (PMID 29966001, 2018). "It has been reported that activating transcription factor 3 (ATF3) is one of the target proteins for ROS and ROS-mediated ATF3 activation induces apoptosis in human colorectal cancer cells." (PMID 29554905, 2018). "Using Western blot, the authors assessed the level of activating transcription factor 3 (ATF3), the protein known to act as a tumor suppressor in colorectal cancer." (PMID 30551667, 2018). "In human colorectal tumors, ATF3 expression is repressed compared to normal adjacent tissue, and ATF3 overexpression can induce apoptosis in colorectal cancer cells." (PMID 27043582, 2016). "The present study was performed to investigate the molecular mechanism by which PFF-A stimulates ATF3 expression and apoptosis in human colorectal cancer cells." (PMID 27043582, 2016). "In this study, we have elucidated the specific mechanism focused on ATF3 of PFF-A for apoptosis because ATF3 has been reported as a key factor for the induction of apoptosis by many phytochemicals in human colorectal cancer." (PMID 27043582, 2016). "Another example is that the overexpression of ATF3 has been shown to reduce the size of tumor xenografts of HCT-116 human colorectal cancer cells placed subcutaneously in nude mice." (PMID 25872784, 2015). "In search for approaches to augment the potential therapeutic efficacy of A. distichum for human colorectal cancer, we investigated the anticancer activity of A. distichum and the role of ATF3 in apoptosis by A. distichum in human colorectal cancer cells." (PMID 25494848, 2014). "Although ATF3 has dual effects in cancer development, ATF3 has been regarded as a major target of cancer chemoprevention in colorectal cancer." (PMID 25338635, 2014). "Among the bioactive compounds, quercetin has been reported to induce ATF3 expression in human colorectal cancer cells, Caco-2." (PMID 25338635, 2014). "ATF3 expression was suppressed in human colorectal cancer and expression of ATF3 induced apoptosis, growth arrest of colorectal cancer cells and Ras-stimulated tumourigenesis." (PMID 25338635, 2014). "ATF3 expression is decreased in human colorectal cancer, and ATF3 overexpression results in apoptosis of human LNCaP prostate cancer cells." (PMID 23591848, 2013). "The importance of EGR1/ATF3 axis in death signalling is supported by recent studies that described an EGR1 driven activation of the pro-apoptotic transcription factor ATF3 in colorectal cancer cells following treatment with anti-neoplastic substances." (PMID 21034493, 2010). "Indole-3-carbinol and CDIM compounds induce proapoptotic gene NAG-1 expression mediated by ATF3 in human colorectal cancer cells." (PMID 17764562, 2007). "FOSB is increasingly regulated by ATF3 from the healthy adjacent region to the core region, and it plays a critical role in regulating inflammatory molecule expression, which influences the therapeutic effects of drugs on colorectal cancer." (PMID 40585960, 2025). "The increased activity of ATF3 (P = 4.89×10−278) drives colorectal cancer cell proliferation." (PMID 40585960, 2025). "Patulin enhances ATF3 expression and promotes apoptosis in colorectal cancer cells." (PMID 38255898, 2024). "Similarly, IHC staining showed that CBS and ATF3 were significantly higher in colorectal cancer hepatic metastasis samples than in adjacent normal tissues." (PMID 38490069, 2024).